GATA4 (GATA binding protein 4)
Diseases named in the same sentence as GATA4 in open-access papers (continued):
Sharing a sentence is not in itself a finding about the gene and the disease.
colon carcinoma (13 papers, 2006 to 2025). "To further define the role of Mll1 in the regulation of Gata4 and secretory cell differentiation, we studied the Wnt-high human colon cancer cells Ls174T and DLD1, from which we had previously established MLL1 knockdown lines." (PMID 35064075, 2022). "To assess the clinical significance of GATA4 in colon cancer, we analyzed the relationship between GATA4 expression and survival probability." (PMID 34987705, 2021). "High levels of Foxa1 expression were observed in poorly differentiated colon cancer, and Gata6, the colon homolog of Gata4, participates in the regulation of stemness by preventing Bmp4-induced differentiation in Wnt-driven colon cancer." (PMID 33349639, 2020). "Gata4/6 transcription factors had previously been reported to repress Bmp4, thereby maintaining colon cancer stemness." (PMID 33349639, 2020). "Caudal homeobox proteins (Cdx1 & Cdx2) and GATA binding protein 4, GATA4) are known activators of claudin-1 promoters in colon cancer." (PMID 31861759, 2019). "We observed a similar trend of induction of pGL3/−1.2Cld-1-driven luciferase activity in HCT116 colon cancer, which was 2.5–3 fold upon overexpression of Cdx1 and GATA4 and ∼4-fold upon overexpression of Cdx2." (PMID 22719836, 2012). "Taken together, we conclude that homeodomain transcription factors Cdx1, Cdx2 and GATA4 regulate claudin-1 gene expression in human colon cancer cells." (PMID 22719836, 2012). "For confirmation, we acquired the ChIP-seq profiles of the GATA4 protein in colon cancer cells." (PMID 35046932, 2021). "Hellebrekers transferred the expression plasmid of GATA4 into RKO and HCT1116 cells, and found that GATA4 could significantly inhibit the proliferation and migration of colon cancer cells." (PMID 34513713, 2021). "An analysis of human colon cancer samples data from The Cancer Genome Atlas (TCGA) showed that higher GATA4 expression correlated with shorter survival in male patients with colon adenocarcinoma (p = 0.0054), though no such correlation was detected in females (p = 0.27)." (PMID 34987705, 2021). "The human shMLL1 colon cancer cells showed a decrease of the expression of FOXA1 and the GATA4 colon homolog GATA6, which we had identified as Mll1-regulated genes in murine β-catGOF; Mll1−/− stem cells." (PMID 33349639, 2020). "Our further studies using full length and/or deletion mutant constructs in two different human colon cancer cell lines, SW480 and HCT116, showed key role of Cdx1, Cdx2 and GATA4 in the regulation of claudin-1 mRNA expression." (PMID 22719836, 2012). "To demonstrate that GATA4 and PIAS1 physically interact in mammalian cells, we performed coimmunoprecipitation experiments in HCT116 colon cancer cells by overexpressing HA epitope tagged GATA4 and FLAG epitope tagged PIAS1." (PMID 22539995, 2012). "In contrast to metaplasias of the proximal gastrointestinal tract, GATA-4 is not present in colon tumors, whereas GATA-6 and Ihh are moderately expressed in colon adenomas, but to a much lesser extent in carcinomas." (PMID 18405344, 2008). "Role of GATA4 in the regulation of colon carcinogenesis is not well studied though limited studies suggested that it may function as a tumor suppressor in the colon cancer." (PMID 22719836, 2012). "Additionally, we saw the same effect for GATA-4 in HCT116 colon cancer cells when the H363Y mutant was expressed, but not the wild type (unpublished data)." (PMID 16596166, 2006).
atrioventricular septal defect (12 papers, 2007 to 2024). "In 42 patients with non-syndromic atrioventricular septal defects (familial as well as sporadic), no GATA4 mutations have been detected." (PMID 17592645, 2007). "It remains unclear if the GATA4 G296S mutation has a role in formation of the endocardial cushions but one family member with the G296S mutation did have an atrioventricular septal defect and other non-related individuals with GATA4 mutations have atrioventricular septal defects." (PMID 22589735, 2012).
cardiac septal defects (12 papers, 2010 to 2025). "In this study, we report the identification of a novel heterozygous missense variant in GATA4 (NM_002052.5:c.907G>T; p.Gly303Trp) in a family affected by septal heart defects and pulmonary stenosis." (PMID 40430071, 2025). "In this study, we report a novel heterozygous missense variant in GATA4, NM_002052.5:c.907G>T (p.Gly303Trp), identified in a family presenting with a spectrum of septal heart defects and pulmonary stenosis." (PMID 40430071, 2025). "Mutations in GATA4, although primarily linked to cardiac septal defects, have also been reported to be associated with congenital pulmonic valve stenosis, including three unrelated familial cases with a p.Gly296Ser mutation." (PMID 31138536, 2019). "Mutations in Gata4 have been associated with cardiac septal defects." (PMID 24058054, 2013). "The GATA4 G296S mutation, which we found altered ERRγ, GATA4, and PGC-1α cooperativity, has been shown to cause cardiac septal defects and cardiomyopathy." (PMID 35418170, 2022). "This study designed to study the association of five single–nucleotide variants of NKX2‐5, GATA4, and TBX5 genes with sporadic nonsyndromic cases of a congenital cardiac septal defect in Egyptian children." (PMID 30834692, 2019). "GATA4 has been identified in familial and sporadic cardiac septal defects." (PMID 25928801, 2015).
Hypertension (12 papers, 2011 to 2025). The presence of chronic increased pressure in the systemic arterial system. "Disruption of GATA4-p300 transcriptional complex formation is associated with inhibition of hypertension responsive genes viz." (PMID 32765954, 2020). "Moreover, the analyses for the other metabolic risk factors revealed the association for two variants with hypertension, further linking risk traits for metabolic syndrome to GATA4 polymorphism." (PMID 24330461, 2013). "We determined whether LVH with hypertension was associated with the acetylation of GATA4 in vivo." (PMID 34444769, 2021). "GATA4 expression also tended to be higher in the hypertension group, although its fold change was lower than that of GATA5 (fold change = 1.33, p = 0.06)." (PMID 38451262, 2024). "In conclusion, we have indicated the therapeutic effect of curcumin on hypertension-induced LVH with preserved ejection function through the decrease in acetylated form of GATA4 in Dahl rats." (PMID 34444769, 2021). "The same authors also showed that the acetylation of GATA4 that normally accompanies hypertension was reduced by curcumin." (PMID 22745783, 2012). "Similarly, variants near GATA4 and members of the HOXB family of transcription factors such as HOXB7 have been associated with hypertension, while HAND2 variants are associated with aortic dimension and atrial fibrillation." (PMID 40931195, 2025). "In addition, curcumin significantly suppressed the expression levels of the hypertension-induced cardiac hypertrophic marker genes as well as the acetylation of GATA4." (PMID 34444769, 2021). "In summary, we have demonstrated that GA lowers systolic blood pressure and LVH in rats with essential hypertension, and that it inhibits cardiac Nox2 expression and the Nox2-induced oxidative stress response through the knockdown of GATA4 or by interfering with the DNA-binding activity of GATA4." (PMID 29142252, 2017). "In our present study, DF treatment and exercise significantly reduced the expression of fibrotic protein markers such as uPA, CTGF, COL1A1, and COL3A1, as well as hypertrophy markers such as NFATC3, GATA4, BNP, and ANP, which indicates that it could attenuate hypertension-mediated myocardial injury." (PMID 35890118, 2022).
pulmonary stenosis (12 papers, 2012 to 2025). "The observation of pulmonic valve stenosis in a mouse model harboring a human disease-causing GATA4 mutation further supported a role for GATA4 in valve development, but the mechanistic basis for this association has not been investigated." (PMID 31138536, 2019). "Impaired contraction in patient-derived hiPS-CMs has been reported in not only HLHS-derived hiPS-CMs but also hiPS-CMs from family members with a pathogenic GATA4-variant causing septal defects and pulmonary stenosis, and hiPS-CMs from patients with pulmonary atresia with intact ventricular septum." (PMID 34208537, 2021). "Although the GATA4 p.Gly296Ser mutation results in specific functional deficits based upon our previous studies, these human genetics findings support that heterozygous loss-of-function of GATA4 contributes to pulmonic valve stenosis." (PMID 31138536, 2019). "GATA4 gene mutations have been demonstrated in many human families and are associated with ASD and pulmonary stenosis." (PMID 25873328, 2015). "Quantitative pulsed Doppler recordings across the pulmonary and aortic valves demonstrated mild aortic stenosis in 4/12 Gata4 G295Ski/wt mice and pulmonary stenosis in 2/12 Gata4 G295Ski/wt mouse." (PMID 22589735, 2012). "The iPSC-CMs of HipSCs with a missense variant in GATA4, which is linked to septal defects and pulmonary stenosis, display a lack of GATA4-TBX5 interactions and an incorrect expression of endothelial cell genes." (PMID 38339013, 2024).
hepatocellular carcinoma (9 papers, 2013 to 2024). A malignant tumor that arises from hepatocytes. "In transformed hepatoma cell lines, GATA4 activates liver-specific genes encoding coagulation factor X, homeobox gene Hex, a cytochrome p450, and hepcidin." (PMID 24367609, 2013). "However, further experiments are needed to address how does liver gain ectopic expression of hematopoietic factor GATA2 with concomitant loss of endoderm factors GATA4 ∼ 6 and how, if that exists, do these factors cooperate or compete with each other in the progression of hepatocellular carcinoma." (PMID 24498120, 2014). "Ectopic expression of GATA4 in hepatocellular carcinoma cells activates NF-kB, resulting in cellular senescence." (PMID 39456519, 2024). "Previously, we found that GATA4 induces mesenchymal-to-epithelial transition and cellular senescence through the NF-κB pathway in hepatocellular carcinoma." (PMID 34583732, 2021). "GATA binding protein 4 (GATA4) has been reported as a potential target of gene therapy for hepatocellular carcinoma (HCC)." (PMID 34583732, 2021). "Also, a previous study has shown that GATA4 promoted oncogenesis through suppression of DKK3 expression in hepatoma cells." (PMID 33013201, 2020). "In terms of Epigenetic modifications, GATA4 is not responsible for forming and maintaining the hepatocellular carcinoma-like phenotype." (PMID 33912455, 2021). "This GATA4/miR125b/DKK3 axis may be a major regulator of growth, migration, invasion, and survival in hepatoma cells, and is therefore a potential therapeutic target or biomarker for progression in HB patients." (PMID 27788486, 2016).
atherosclerosis (8 papers, 2011 to 2024). A disease characterized by the build-up of fatty material and calcium deposition in the arterial wall resulting in partial or complete occlusion of the arterial lumen. "Altogether, these observations furnish support for the notion of a contribution of some interactions of metabolic risk traits with GATA4 to the disease pathways leading to atherosclerosis, an assertion which requires further investigation." (PMID 24330461, 2013). "For example, GATA4 represses the transcriptional activity of apolipoprotein(a) gene, high levels of which are an independent risk factor for premature atherosclerosis and stroke." (PMID 21673957, 2011). "Since the proliferation of VSMC is a vital phenotypic modulation characteristic in VSMC dedifferentiation and is closely linked to atherosclerosis, we wondered if GATA4 account for the development of CAD via regulating the proliferation of coronary artery VSMC." (PMID 34545275, 2021). "Further, endothelial-specific deletion of Gata4 or Twist1 reduces the lesion size in atherosclerotic mice indicating that the Gata4–Twist1–Snai1 pathway contributes to atherosclerosis." (PMID 34901211, 2021). "This is based on the observation that expression of BMAL1 or GATA4 reduced atherosclerosis to similar extents (∼75%), whereas Shp expression reduced it by ∼50%." (PMID 27721414, 2016). "Since, Bmal1 and Gata4 affect both lipoprotein production and cholesterol secretion to bile, it is likely that their higher efficacy in reducing atherosclerosis compared with Shp is secondary to their effects on both these processes." (PMID 27721414, 2016). "Genetic deletion of GATA4 or TWIST1 in EC reduced lesion area in the aorta, indicating that GATA4–TWIST1 signaling contributes to atherosclerosis." (PMID 27245171, 2016). "GATA4–TWIST1 signaling in EC drives atherosclerosis through several mechanisms." (PMID 27245171, 2016). "Besides, the ubiquity of GATA4 in the myocardium also raises fundamental questions with respect to possible diversity in its cardiac-related function(s) and its involvement in other cardiovascular disease pathways, such as those leading to atherosclerosis." (PMID 24330461, 2013). "However, our studies involving overexpression of BMAL1, SHP or GATA4 in L-Bmal1−/−Apoe−/− mice indicate that a combination of hepatic lipoprotein over production and reduced biliary cholesterol excretion might contribute additively to atherosclerosis." (PMID 27721414, 2016). "Thus, apart from the demonstrated association of GATA4 polymorphism with dyslipidaemia, our results also point to interrelationships of the two disease components with CAD/MI, which may explain partly how these diseases lead to atherosclerosis." (PMID 24330461, 2013). "We suggest therefore that the behavior of EC at atheroprone sites is a reflection of an early developmental stage and that developmental genes including GATA4 and TWIST1 could be novel therapeutic targets in atherosclerosis." (PMID 27245171, 2016). "Given their roles in regulating inflammation and EC proliferation in response to low shear stress, we hypothesized that GATA4 and TWIST1 may influence the initiation of atherosclerosis." (PMID 27245171, 2016). "We wished to know whether GATA4–TWIST1 signaling influences EC dysfunction and the initiation of atherosclerosis at low shear sites." (PMID 27245171, 2016). "Thus, overexpression of GATA4 enhances hepatic expression of Abcg5 and Abcg8, and cholesterol excretion to the bile in L-Bmal1−/−Apoe−/− and Bmal1fl/flApoe−/− mice, while reducing MTP expression and atherosclerosis." (PMID 27721414, 2016).
Hyperglycemia (8 papers, 2011 to 2025). An increased concentration of glucose in the blood. "Maternal hyperglycemia and metabolic syndromes during pregnancy may influence the expression of cardiogenic transcription factors (e.g., GATA4, NKX2-5), thereby predisposing the fetus to structural cardiac anomalies." (PMID 41383574, 2025). "A recent study demonstrated that acute hyperglycemia and the diabetic conditions induce degradation of cardiac GATA4, an abundant transcription factor in heart that functions mainly as regulator of ANP, BNP, and α- and β-MHC expression." (PMID 22474596, 2012). "Another study also showed that hyperglycemia can cause systolic dysfunction and a higher expression of cTnI in cardiomyocytes through ROS, enhancing MEK/ERK-induced GATA-4 phosphorylation and accumulation in the cell nucleus." (PMID 22257425, 2012). "In conditions acutely mimicking the diabetic state with hyperglycemia or with chronic diabetes, degradation of cardiac GATA4 levels is accelerated." (PMID 22474596, 2012). "We have demonstrated that hyperglycemia-induced ROS activate the MEK/ERK pathway to increase GATA-4 phosphorylation for higher transcription." (PMID 21702924, 2011). "The effects of hyperglycemia on the protein levels of TnI and phospho-GATA-4 were further characterized in cultured neonatal rat cardiomyocytes and H9c2 cells exposed to various concentrations of glucose in vitro." (PMID 21702924, 2011). "Hyperglycemia can cause systolic dysfunction and a higher expression of cTnI in cardiomyocytes through ROS, enhancing MEK/ERK-induced GATA-4 phosphorylation and accumulation in the cell nucleus." (PMID 21702924, 2011). "Degradation of GATA4 by hyperglycemia is induced by ROS and ubiquitination by ubiquitin-proteaosomes, and a benefit of exercise may be related to reduced expression of E3-ubiquitin ligase MURF1." (PMID 27268060, 2016). "Hyperglycemia per se has been previously proposed as a mechanism depleting cardiac GATA4." (PMID 22474596, 2012). "Thus, we continued our studies of H9c2 cells to investigate the possible mechanisms of HG-induced TnI and phosphor-GATA-4 protein expression in hyperglycemia-treated cells." (PMID 21702924, 2011). "In-utero exposure to maternal hyperglycemia or hypoxia can interfere with cardiac looping and septation via dysregulation of NKX2.5, GATA4, and TBX5 gene expression." (PMID 41383574, 2025). "However, hyperglycemia failed to increase the expression of cTnI when GATA-4 was silenced by small interfering RNA (siRNA) in H9c2 cells." (PMID 21702924, 2011). "The role of GATA4 and exercise training on the OT/OTR system is further complicated by our recent findings showing that expression of this transcription factor is not altered by the effects of hyperglycemia or obesity in hearts of ob/ob mice." (PMID 27268060, 2016).
Arrhythmia (7 papers, 2015 to 2025). Any cardiac rhythm other than the normal sinus rhythm. "Moreover, mutations in Gata4 and -6 are responsible for congenital heart defects including AV canal defects and arrhythmias in human and mouse, implicating their function in conduction system tissues." (PMID 26126786, 2015). "We identified for the first time a novel M310T mutation in the GATA4 gene that is located in the NLS region and leads to family ASD with arrhythmias." (PMID 33413087, 2021). "Mutations in both GATA4 and its family member GATA6 in patients have been associated with arrhythmias and defects in atrial, ventricular, and AV septation." (PMID 26126786, 2015).
atrial fibrillation (7 papers, 2017 to 2025). A disorder characterized by an electrocardiographic finding of a supraventricular arrhythmia characterized by the replacement of consistent P waves by rapid oscillations or fibrillatory waves that vary in size, shape and timing and are accompanied by an irregular ventricular response. "This extended gene network contained a number of transcription factors (Tbx5, Hand2, Fhl2, and Gata4) and ion/calcium handling genes (Ank2, Cacna2d2, Scn5a, Kcnd2, Kcnj5, Myoz2, Casq2, Csrp3, and Gja3) of interest in the context of atrial fibrillation." (PMID 28720711, 2017). "However, there are exceptions to this trend such as is observed in atrial fibrillation, where GATA4, GTF2I, and CASZ1 are both CVD proteins and DOX-correlated hub proteins." (PMID 40469117, 2025). "Furthermore, GWAS of multiple cardiac traits, such as atrial fibrillation and PR interval, identified loci associated with embryonic development-associated genes and genes whose mutations are known to cause serious heart defects, such as TTN, GATA4, MYH6, NKX2-5, PITX2, and TBX52–4." (PMID 36854752, 2023). "Notably, genetic and familial studies indicate cardiac transcription factors including GATA4, TBX5, and NKX2.5 in atrial fibrillation pathogenesis." (PMID 38049901, 2023). "MiR-26 can also suppress atrial fibrillation (AF) and cardiomyocyte hypertrophy by targeting β-MHC, GSK3β, GATA4, KCNJ2, and PLCβ1." (PMID 38195542, 2024).